ICAM1 (intercellular adhesion molecule 1)
Diseases named in the same sentence as ICAM1 in open-access papers (continued):
Sharing a sentence is not in itself a finding about the gene and the disease.
depression (continued). "Further, we analyzed the link between ICAM-1 induced neuroinflammation and neurodegeneration with sensorimotor function impairment and depression and anxiety-like psychological stress behavior." (PMID 34135004, 2021). "Sera from patients with depression damage the endothelial cells in vitro, such as increased level of intercellular adhesion molecule-1 (ICAM-1), lower level of endothelial nitric oxide synthase (eNOS) and higher reactive oxygen species (ROS) production." (PMID 34421539, 2021). "ICAM1 mRNA levels were also increased in patients who reported lifetime depression (t = −2.36, df = 49, p = 0.022)." (PMID 33133060, 2020). "This review will focus on the role of ICAM-1 in schizophrenia, depression, bipolar disorder, and dementia." (PMID 31824303, 2019). "ICAM1 and OSMR have been linked to depressive episodes in a recent study." (PMID 39911945, 2025). "We did however find reduced ICAM-1 in the insula in those with co-morbid depression." (PMID 39526037, 2024). "A decrease in ICAM-1 expression in the anterior insula was seen in the AD + depression group." (PMID 39526037, 2024). "The cytokine ICAM-1, as an adhesion molecule, may be involved in the depression pathomechanism according to the vascular hypothesis of depressive disorder." (PMID 37921965, 2023). "Likewise, the ICAM-1:collagen-IV ratio was unchanged in the later-life depression group compared to controls in the OFC." (PMID 37700368, 2023). "Similar to COPD, IL-18, TGF-β, RANTES, ICAM-1, and uPAR have been explored in depressive disorder." (PMID 37921965, 2023). "In the current study, we demonstrated that two biomarkers, ICAM-1 and PECAM-1, were significantly higher in the serum of patients associated with cognitive dysfunction, depression, vestibulocerebellar ataxia, and in the group of patients following chemotherapy." (PMID 35366289, 2022). "Interestingly, patients with depression have increased ICAM-1 levels in serum and the dorsolateral prefrontal cortex." (PMID 33945102, 2021). "Finally, it is important to keep in mind that the overexpression of ICAM-1 is observed in a wide range of diseases and inflammation, even in depressive disorders." (PMID 34206599, 2021). "Because accompanying depressive states often occur in somatic disorders and especially in inflammatory disorders—one of the starting points for research on the role of inflammation in depression—the function of ICAM-1 has often been studied in depressed states comorbid to somatic disorders." (PMID 31824303, 2019). "Although the blood level of soluble ICAM-1 (sICAM-1) might be lower in acute unmedicated schizophrenia, it has been reported to be increased in many other psychiatric conditions, such as major depression, bipolar disorder, and dementia." (PMID 31824303, 2019). "The authors found lower ICAM-1 expression in suicide victims with depression than in controls." (PMID 31824303, 2019). "The CNS expression of sICAM-1 may best reflect the relationship between the psychopathological state of depression and the role of ICAM-1." (PMID 31824303, 2019). "Happiness, as distinct from negative emotions such as depression/anxiety, is associated with lower intercellular adhesion molecule-1 (ICAM-1) promoter methylation." (PMID 27827896, 2016). "Since one clinical study did find elevated levels of both s-ICAM-1 and sVCAM-1 in 33 elderly patients with depression, this might be related to insufficient power in our study or less contribution of ischemia-induced inflammation in our patients with AUD and depression." (PMID 32372985, 2020). "For instance, studies of serum IL-6, ICAM-1, and VCAM-1 levels in AD patients and depression patients show some differences." (PMID 38247923, 2024). "The study of intercellular adhesion molecule-1 (ICAM-1) and SIRT1, a member of the sirtuin family with nitric oxide (NO), is emerging in depression and anxiety." (PMID 38396638, 2024).
depression (continued). "Intercellular adhesive molecule (ICAM)-1 levels were significantly higher in COPD patients and lower in depressive disorder patients than in controls." (PMID 37921965, 2023). "The scope of this study was to measure and compare the profiles of IL-18, TGF-β, RANTES, ICAM-1, and uPAR among stable COPD patients, recurrent depressive disorder (rDD) patients, and healthy controls." (PMID 37921965, 2023). "We examined and confronted the ranges of IL-18, TGF-β, RANTES, ICAM-1, and uPAR among stable COPD patients, recurrent depressive disorder (rDD) patients, and healthy controls." (PMID 37921965, 2023). "Our study found a statistically significant increase in ICAM-1, PECAM-1 in the blood of women with depression." (PMID 35366289, 2022). "Increased serum levels of soluble ICAM-1 and PECAM-1 are observed in a number of neuropsychiatric disorders (i.e., depression, bipolar disorder, dementia, and progressive vascular cognitive disorders)." (PMID 35366289, 2022). "ICAM-1 deletion in TBI improves sensorimotor, depression, and anxiety-like behavior with significant upregulation of norepinephrine (NE), dopamine (DA) D1 receptor (DAD1R), serotonin (5-HT)1AR, and neuropeptide Y (NPY)." (PMID 34135004, 2021). "Furthermore, our study highlighted the role of relatively new markers for neuroinflammation by focusing on the roles of ICAM-1, SIRT1 and NO in psychiatric disorders, namely stress, anxiety and depression." (PMID 38396638, 2024). "Previous studies looking into depression, not in the context of AD, have reported increased ICAM-1 (Müller, 2019)." (PMID 39526037, 2024). "Similarly, intercellular adhesion molecule-1 (ICAM-1), interleukin (IL)-1β, IL-6, IL-10, and tumor necrosis factor (TNF)-α are significantly increased in depression and bipolar disorder, while interferon (IFN)-γ is significantly decreased." (PMID 37628746, 2023). "In patients suffering from depression, soluble forms of ICAM-1 and VCAM-1 were increased, as opposed to reduced levels of BDNF." (PMID 32372985, 2020). "Unlike depression, significant elevation of ICAM-1 was detected in our early-stage AD cohort." (PMID 40179065, 2025). "Our data indicate that ICAM-1 activation following TBI induced a significant impairment in sensorimotor function as monitored by rotarod and grid walk test and severely exacerbate depression and anxiety-like psychological stress as monitored by the sucrose preference test and the light-dark test." (PMID 34135004, 2021). "Because ICAM-1 is expressed by choroid epithelial cells and is thought to support immune cell trafficking in the ChP, this finding might be an indication of decreased immune cell trafficking through the BBB in depression and suicide." (PMID 31824303, 2019). "As ICAM-1 is expressed by choroid epithelial cells and is thought to support immune cell trafficking in the ChP, this finding might be an indication of attenuated immune cell trafficking through the BCSFB in depression and suicide." (PMID 26539126, 2015). "The study found significant increases in the expression of ICAM-1 (and additional CAMs) in the gray matter of the dorsolateral prefrontal cortex (DLPFC) in the unipolar depression group but no comparable differences between groups in the anterior cingulate cortex (ACC) or occipital cortex." (PMID 31824303, 2019). "However, the lower concentration of ICAM-1 in depressive patients is not consistent with the inflammatory and ICAM-related vascular hypothesis of depressive disorder." (PMID 37921965, 2023).
colon carcinoma (35 papers, 2008 to 2025). "Using a colon cancer liver metastasis model in ICAM-1-deficient (ICAM-1−/−) mice and their wild-type littermates, we found that loss of ICAM-1 accelerated liver metastasis of colon carcinoma cells." (PMID 26068788, 2015). "In this study, we evaluated the molecular mechanisms underlying the roles of SDF-1 in modulating ICAM-1 expression and cell adhesion to HUVECs in colon cancer cells." (PMID 23098564, 2012). "Combined, these data mining and direct expression assessment in human colon cancer suggest that ICAM-1 expression is negatively associated with metastasis and may be a useful indicator of prognosis in patients with colon cancer." (PMID 26068788, 2015). "Thus, celecoxib was shown to cause inhibition of ICAM-1 expression in colon cancer cells and a decreased adhesion to fetal calf serum (FCS)-coated plastic wells with both events mediated via a COX-2-independent pathway." (PMID 26513172, 2015). "To determine whether ICAM-1 expression was associated with colon cancer in humans, we first performed data mining and analyzed ICAM-1 transcript by using the publicly available Oncomine database." (PMID 26068788, 2015). "The engagement of NKG2D receptors with MICA/B and ICAM-1 on the surface of colon cancer cells triggers activation, leading to the release of perforin and granzyme B by activated γδ T cells." (PMID 39253082, 2024). "ICAM-1 is a cell surface adhesion glycoprotein that mediates leukocyte adhesion and plays a role in the development of colon cancer." (PMID 39758846, 2024). "The possible mechanism is that MTCAFs activate the AKT and STAT3 signaling pathways in colon cancer cells via the ICAM-1/LFA-1axis." (PMID 36016615, 2022). "One of the critical problems is the molecular mechanism of ICAM-1 derived from MTCAFs action on colon cancer cells in our study." (PMID 36016615, 2022). "Collectively, our findings suggested that ICAM-1 serves as an adapter protein regulating malignancy of colon cancer." (PMID 35487888, 2022). "By contrast, LFA-1 and ICAM-1 upregulated by IL-18 can facilitate the eosinophil-mediated tumoricidal activity against a colon carcinoma cell line." (PMID 33336008, 2020). "Pectin extracted from potatoes has demonstrated a significant reduction in cellular proliferation of colon cancer cells through the suppression of intercellular adhesion molecule 1 (ICAM 1) expression." (PMID 31936288, 2020). "Our research supports the role of butyrate to reduce ICAM-1 expression as observed in the intestine of burned rats, stimulated chondrocytes, glomerular mesangial cells, colon cancer cells, and endothelial cells." (PMID 32121422, 2020). "Intercellular adhesion molecule 1 (ICAM1) is found to be involved in the colon cancer cell proliferation." (PMID 30186855, 2018). "ICAM-1 expression was markedly increased in colon carcinoma, which was mainly distributed not only in the cytoplasm and membrane of tumor cells but also in tumor-infiltrating leukocytes." (PMID 26068788, 2015). "We report that ICAM-1 expression is inversely associated with macrophage infiltration and the metastasis index in human colon tumors by combining Oncomine database analysis and immunohistochemistry for ICAM-1." (PMID 26068788, 2015). "Expression of ICAM-1 in colonic ECs from patients with colonic carcinoma and inflammatory bowel disease was increased by two fold compared to normal colonic ECs." (PMID 22291924, 2012). "In summary, our data contribute new information about the mechanisms by which SDF-1 induces ICAM-1 expression and cell adhesion to the endothelium in colon cancer cells." (PMID 23098564, 2012). "Our results also reveal that the angiogenesis-stimulating potential induced by soluble ICAM-1 on LFA-1-expressing colon carcinoma cells was regulated by cyclooxygenase-2." (PMID 18844982, 2008). "Our study also shows that recombinant soluble ICAM-1 induced VEGF production from LFA-1-expressing colon cancer cells." (PMID 18844982, 2008).
colon carcinoma (continued). "In clinical colon cancer specimens, we found that ICAM-1 was highly expressed and related to shorter disease-free survival, which might act as an indication for the progression of clinical colon cancer." (PMID 36016615, 2022). "Taken together, ICAM-1 plays a critical role in regulating tumor growth and metastasis, which could be a potential therapeutic target in colon cancer." (PMID 36016615, 2022). "Thus, it induces transendothelial neutrophil migration and increases the expression of intercellular adhesion molecule-1 (ICAM-1) on colon cancer cells resulting in extensive leukocyte adhesion to these cells." (PMID 29850390, 2018). "Moreover, analysis of ICAM-1 expression in primary tumors and metastasis formation revealed that patients who had lymph node or liver metastasis and local recurrence within 3 years showed markedly decreased ICAM-1 expression in colon cancer tissues." (PMID 26068788, 2015). "To determine whether host-derived ICAM-1 in the tumor microenvironment affects tumor metastasis, we used a colon cancer liver metastasis model, in which SL4 mouse colon cancer cells were injected into the spleens of wild-type (WT) and ICAM-1−/− mice." (PMID 26068788, 2015). "Importantly, the expression of ICAM-1 in primary tumors from colon cancer patients with liver metastasis was significantly lower than those of lesions without liver metastasis." (PMID 26068788, 2015). "Moreover, there was a strict correlation between LFA-1 expression and VEGF production levels in CT26 colon carcinoma cells activated by soluble ICAM-1." (PMID 18844982, 2008). "However, our results show for first time that soluble ICAM-1 can directly confer angiogenic-stimulating properties to LFA-1-expressing colon carcinoma cells grown in the hepatic microenvironment." (PMID 18844982, 2008). "Unlike other microvessels, hepatic sinusoids exhibit elevated base-line expression of ICAM-1 under normal physiological conditions, suggesting that cancer cell expression ofLFA-1 contributes to retention and seeding of liver-infiltrating colon carcinoma cells." (PMID 18844982, 2008). "Another study suggests that polysaccharides with content of RG-I and HG variation could inhibit colon cancer cells proliferation by decreasing ICAM1 expression, a protein responsible for cell–cell interaction and cell–ECM interaction independent of galectin-3 expression." (PMID 29185464, 2017). "To investigate directly whether ICAM-1 expression is associated with the tumor microenvironment and colon carcinoma progression clinically, we used human colon carcinoma and adjacent normal colon tissues to examine ICAM-1 expression concurrently with infiltrating TAMs." (PMID 26068788, 2015). "In cellular immunotherapy, bispecific CAR-T cells targeting EpCAM and intercellular adhesion molecule 1 (ICAM-1) have demonstrated remarkable efficacy, while EpCAM-CAR-NK92 cells exhibit a synergistic therapeutic effect with regorafenib in colon cancer." (PMID 38791091, 2024). "LPS also increased COX2, CXCL1, ELK1, ICAM1, TNFSF10 and ZFAND5 but decreased BCL2L1, CYP19A1 and E2F1 mRNA levels in the colon cancer cells." (PMID 37705049, 2023). "qPCR showed that LPS increased CXCL1, ELK1, ICAM1 and ZFAND5 mRNA levels, but decreased BCL2L1 and E2F1 mRNA levels in the colon cancer cells." (PMID 37705049, 2023). "Bioinformatics and Western blotting analysis indicated a positive correlation between intercellular adhesion molecule-1(ICAM-1) and the progression of colon cancer." (PMID 36016615, 2022). "The expression levels of FAK, p-FAK, ICAM1, and VCAM1 were also upregulated with the overexpression of Sphk1 but downregulated with the reduction of Sphk1 in colon cancer cells." (PMID 28991193, 2017). "Because COX-2 contributes to colon carcinoma cell production of VEGF, in some experiments, both untreated and soluble ICAM-1-treated monolayer- and 3D-cultured CT26 cells received 1 μg/ml COX-2 inhibitor Celecoxib for 18 hours." (PMID 18844982, 2008).
colon carcinoma (continued). "In addition, ICAM1 neutralizing antibodies have also been found to inhibit SRC and STAT3 pathways and inhibit colon tumor metastasis and angiogenesis." (PMID 39971940, 2025). "Following coculture, the expression of intercellular adhesion molecule (ICAM-1, CD54) significantly increased in both neutrophils and various colon cancer cells, indicating stronger adhesion between neutrophils and colon cancer cells upon NET generation, creating a tightly interconnected system." (PMID 40963981, 2025). "Therefore, we found that MTCAF-derived ICAM-1 promotes the progression by activating the STAT3 and AKT signaling in colon cancer cells." (PMID 36016615, 2022). "To determine whether ICAM-1 is highly expressed as an oncogene in CRC patients, we analyzed ICAM-1 expression using the gene expression omnibus (GEO) online database and colon cancer tissue microarray." (PMID 35487888, 2022). "A reverse relationship between ICAM-1 expression and macrophage infiltration was observed in comparison to primary colon carcinoma with and without liver metastasis." (PMID 26068788, 2015). "By contrast, ICAM-1 expression in primary tumors from stage III and IV colon cancer patients was significantly decreased compared with that of primary lesions from stage I and II colon cancer patients." (PMID 26068788, 2015).